CD38 (CD38 molecule)
Diseases named in the same sentence as CD38 in open-access papers (continued):
Sharing a sentence is not in itself a finding about the gene and the disease.
acute lymphoblastic leukemia (40 papers, 2012 to 2026). Leukemia with an acute onset, characterized by the presence of lymphoblasts in the bone marrow and the peripheral blood. "Researchers are actively expanding the use of daratumumab for other CD38+ blood cancers, including acute lymphoblastic leukemia (ALL), natural killer/T-cell lymphoma (NKTCL), and acute myeloid leukemia." (PMID 35765110, 2022). "Various preclinical studies and ongoing clinical trials aimed to evaluate the efficiency of CD38 antibodies in hematological malignancies such as NK/T cell lymphoma and acute lymphoblastic leukemia." (PMID 34226519, 2021). "Therefore, we aimed to evaluate sGRP78 in pediatric patients with B-lineage acute lymphoblastic leukemia (B-ALL) at diagnosis and investigate its association with stem cell markers (CD34 and CD38), lineage markers (CD10 and CD19)." (PMID 35149705, 2022). "Similarly, in the blast phase of Ph+ CML, LSC appear to express CD38, and the same holds true for Ph+ and Ph− acute lymphoblastic leukemia (ALL)." (PMID 31470642, 2019). "We present a case whereby use of the anti-CD38 monoclonal antibody daratumumab was able to successfully reduce DSA via its action of the cell surface glycoprotein highly expressed on plasma cells in a multiparous patient with early T-cell precursor acute lymphoblastic leukemia (ETP-ALL)." (PMID 41659863, 2026). "In a humanized T-cell acute lymphoblastic leukemia (T-ALL) model, CD38 allogeneic universal CAR-T cells demonstrated superior survival rates and tumor clearance with reduced inflammatory responses." (PMID 39856752, 2025). "The robust and stable expression of CD38 in T‐cell acute lymphoblastic leukemia (T‐ALL) blasts makes CD38 chimeric antigen receptor (CAR)‐T/natural killer (NK) a potential therapy for T‐ALL." (PMID 37485647, 2023). "In the blast phase (blast crisis) of chronic myeloid leukemia and in acute lymphoblastic leukemia, NSG‐engrafting stem cells are also found in both, the CD34+/CD38− and CD34+/CD38+ subfraction of leukemic cells." (PMID 32657052, 2020). "Similarly, in Acute Lymphoblastic Leukemia (ALL), combining CD38 antibodies like daratumumab with chemotherapy regimens has yielded promising outcomes, particularly for patients with high CD38 expression." (PMID 40057636, 2025). "Our present study attempts to test for the sensitivity of the MRD “lite” panel using CD38, CD10, CD19, CD34, and CD45 for the diagnosis of residual disease in B-cell acute lymphoblastic leukemia (B-ALL)." (PMID 39634988, 2024). "Could the lack of expression of the CD38 antigen on lymphoblasts in B-cell precursor acute lymphoblastic leukemia correspond to forms that are closer to LSCs, and thus less mature and more resistant to treatment?" (PMID 37675394, 2023). "Additionally, CD38+ CAR-T cells have shown promising efficacy for treating MM and acute lymphoblastic leukemia (ALL)." (PMID 39856752, 2025). "CD38-CAR T cells dramatically inhibited the growth of CD38high MM, mantle cell lymphoma (MCL), Waldenstrom’s macroglobulinemia (WM), T-cell acute lymphoblastic leukemia (T-ALL), and NK/T-cell lymphoma (NKTCL) in vitro and in mouse xenografts." (PMID 35765110, 2022). "XmAb968 is another CD38 × CD3 TCE with optimized relative affinities for both CD3 and CD38, currently in a phase 1 trial recruiting patients with T cell acute lymphoblastic leukemia (T-ALL) (NCT05038644), since CD38 expression in leukemic blasts of T-ALL has been found to be robust." (PMID 37501154, 2023). "In B-cell precursor acute lymphoblastic leukemia in children, the presence of CD34+CD38− lymphoblasts at the diagnosis does not affect the first remission of the disease." (PMID 37675394, 2023).
AIDS (36 papers, 2008 to 2025). A syndrome resulting from the acquired deficiency of cellular immunity caused by the human immunodeficiency virus (HIV). "A pioneering study showed high CD38 expression on CD8+ T cells as a biomarker for progression to acquired immunodeficiency syndrome (AIDS) and increased risk of death." (PMID 33477581, 2021). "Elevated levels of the T-cell activation marker CD38 were observed in the first AIDS-associated Pneumocystispneumoniae cases." (PMID 23874739, 2013). "Early after HIV infection, the expression of CD38 increased in CD4+ and CD8+ T lymphocytes, and high proportions of the CD8+CD38+ subpopulation were associated with progression to acquired immune deficiency syndrome in adults." (PMID 31963337, 2020). "Lower CD4+ and higher CD38+CD8+% resulted independently associated with AIDS presentation." (PMID 22110905, 2012). "It has been postulated that higher levels of CD8+ CD38+ T-cells may be associated with poor prognosis and were found to be elevated in individuals who have progressed to AIDS." (PMID 18923697, 2008). "Subjects with AIDS/VL had more CD3+CD4+CD38+HLA-DR+ activated T cells when compared to recovered VL (p = 0.0004), HIV (p = 0.0001), and DTH+ (p<0.0001)." (PMID 40096173, 2025). "CD38 and HLA-DR are markers of cell activation and high levels of these markers were observed in subjects with VL, AIDS/VL and Asympt HIV/Leish." (PMID 40096173, 2025). "Study have shown that HIV-infected individuals with normal CD4+ T cell counts tend to develop to the stage of AIDS more quickly if their CD38 expression levels are higher." (PMID 33820568, 2021). "In the multicenter AIDS cohort study, CD38 expression was a better predictor of HIV disease progression than other markers of immune activation." (PMID 33820568, 2021). "Salmon module showed a strong positive correlation with AIDS progression including CD38 and ISGs which is consistent with DEG and GSEA analysis." (PMID 30665429, 2019). "The activated CD8+ T-cells which express HLA-DR and CD38 antigens are better indicators of AIDS and death than either CD4+ T-cell count or plasma viral load." (PMID 30034377, 2018). "Chronic immune activation is proposed to be a key determinant of AIDS pathogenesis, and was marked by CD38 and HLA-DR in this study." (PMID 29511144, 2018). "A 6-month cohort study of 34 outpatients with HIV/AIDS tested the granule’s effects on regulation of immune activation molecules CD38 and human leukocyte antigen-D related to CD4 + T and CD8 + T cells." (PMID 26699285, 2015). "It has been previously demonstrated how CD38+CD8+ phenotype has predictive value for progression to AIDS, even after adjustment for CD4+ levels, and it has been proposed as surrogate marker to clinical monitoring of HIV infection." (PMID 22110905, 2012). "In the present study we have shown that leishmaniasis/HIV-AIDS patients displayed elevated levels of CD38 on CD8+ T cells levels in relation to HIV-1 infected patients without leishmaniasis." (PMID 21171992, 2010). "Noteworthy, increased expression of CD38 on the surface of CD8+ T cells have long been considered an even better prognostic predictor of progression to AIDS and response to HAART than HIV viral load itself." (PMID 20028500, 2009). "Additionally, the same correlations have been observed for Ki67+ in CD4+ T cells, while immune activation (HLA-DR+, CD38+) in CD4+ T cells has been detected as highest in AIDS individuals." (PMID 38420260, 2023). "However, during chronic viral infections maintaining these levels of CD38+HLA-DR+ leads to increased expression of molecules related to exhaustion and apoptosis and both elevated percentages and absolute number of CD38+HLA-DR+ predict the progression to AIDS." (PMID 36723505, 2023). "Indeed, T cell activation (defined as the expression of CD38 on the T cells) is one of the strong predictors of progression to AIDS." (PMID 25187947, 2014).
AIDS (continued). "This apparent state of basal immune hyper-activation in the infected host is evidenced by increased expression of activation markers, such as CD38, HLA-DR and Ki67, of which CD38 is considered the most reliable surrogate marker for immune activation, disease progression to AIDS, and death." (PMID 20569472, 2010). "Finally, we showed that NK cells overexpressed CD38, which is related to progression to AIDS." (PMID 31447833, 2019). "The immunological patterns associated with AIDS presentation independently of demographic factors were of course lower CD4+% T cells (AOR 0.996 for each unit more, 95%CI 0.993–0.998, P = 0.008) but also higher CD38+CD8+% (AOR 1.049 for each unit more, 95%CI 1.004–1.096, P = 0.033)." (PMID 22110905, 2012). "The pathologies of AIDs have been extensively investigated to favor mechanism of action (MOA) of anti-CD38 mAb, featured with potency to reduce autoantibody secretion via CD38-positive (CD38+) cells depletion." (PMID 38765013, 2024). "Elevated CD8+CD38+ and CD8+HLA-DR+ expression persists throughout HIV infection and has prognostic significance for progression onto AIDS." (PMID 36723505, 2023). "Here we show that Breg cells (CD19+CD24++CD38++), as well as B cells expressing PD-L1 (CD19+PD-L1+ cells), are elevated prior to AIDS-NHL diagnosis." (PMID 31253857, 2019). "High proportions of CD38+CD8+ T cells were considered as a marker of poor response to therapy and prognosis in AIDS." (PMID 26886066, 2016). "CD38 has been used to assess chronic immune activation and levels correlate with disease progression in HIV infection and AIDS." (PMID 25033210, 2014). "Higher CD8+%, lower CD127+CD4+%, higher CD95+CD8+%, CD38+CD8+%, and CD45R0+CD38+CD8+% characterized LP/AHD/AIDS presentation." (PMID 22110905, 2012). "CD38 is a marker of cellular activation and its elevated expression on CD8+ T-cells and in the context of HIV infection, is considered a predictor marker in the progression to AIDS and also it has been postulated as a marker of clinical management in PLWHIV." (PMID 40452022, 2025). "Here we show that numbers of both Breg cells (CD19+CD24++CD38++ cells) and CD19+PD-L1+ cells were elevated in the peripheral circulation of HIV+ subjects prior to AIDS-NHL diagnosis, when compared to the levels seen in HIV+ controls who did not develop AIDS-NHL." (PMID 31253857, 2019). "However, the frequency of CD38 expressed by the CD8+ T cell subset was much higher in AVL/HIV-AIDS cases (median 93.5%, [87%-97.9%]) than in patients with ATL/HIV-AIDS (median 77%, [69%-83.6%], p < 0.001)." (PMID 21171992, 2010). "Expression of CD38 on CD8+ T lymphocytes was significantly higher in AVL or ATL/HIV-AIDS cases compared to HIV/AIDS patients without leishmaniasis or healthy subjects." (PMID 21171992, 2010). "We observed that the majority of the PD-L1+ B cells had a phenotype consistent with that of Breg cells (CD19+CD24++CD38++), indicating that these PD-L1+ B cells are a subpopulation of the so-called Breg cell population, at least in these HIV+ subjects who went on to develop AIDS-NHL." (PMID 31253857, 2019). "It was seen that the number of CD19+CD24++CD38++and CD19+PD-L1+cells was significantly elevated in cases 1–4 years prior to AIDS-NHL diagnosis, compared to controls, raising the possibility that these cells may play a role in the etiology of AIDS-NHL." (PMID 31253857, 2019). "The negative correlation between levels of activated CD4 + CD38 + HLA-DR + T cells and BMI in ART-naïve PLWH is consistent with this immune marker and wasting occurring with progression to AIDS." (PMID 38310301, 2024). "Interestingly, CD38 levels observed in co-infected patients were much higher than those seen in cured AVL and ATL patients without HIV/AIDS (unpublished data)." (PMID 21171992, 2010).
diabetes (34 papers, 2004 to 2025). "In our study, we found that the expression levels of Sirt3 and FOXO3a were significantly increased in the hearts of CD38-deficient mice or cardiomyocytes under the condition of diabetes." (PMID 37958991, 2023). "The results showed that the expression levels of NLRP3, caspase 1, IL-1β and IL-18 were increased in CD38flox mice with diabetes compared with the normal group, whereas CD38 deficiency significantly decreased the expression of these genes at the mRNA level." (PMID 37958991, 2023). "Meanwhile, CD38 deficiency also significantly decreased the diabetes-induced increase in the Bax/Bcl2 ratio, which was an indicator of apoptosis in mice." (PMID 37958991, 2023). "Our results showed that CD38 deficiency improved cardiac function, exemplified by increased ejection fraction and shortening fraction under diabetes." (PMID 37958991, 2023). "In conclusion, we demonstrated that CD38 deficiency protected mice from diabetes-induced diabetic cardiomyopathy by reducing pyroptosis and apoptosis via activating NAD+/Sirt3/FOXO3a signaling pathways." (PMID 37958991, 2023). "This was observed in diabetes-prone NOD mice, in which CD38 deficiency was accompanied by an accelerated onset of diabetes." (PMID 26042119, 2015). "Moreover, we also observed that the expression levels of NLRP3 and cleaved IL-1β were up-regulated in heart tissues of CD38flox mice with diabetes, but their expression levels were reduced in the CD38-deficient group compared with control mice under diabetes." (PMID 37958991, 2023). "In addition, CD38 deficiency reduced the diabetes-induced increase in LDH activity in the serum compared with the control." (PMID 37958991, 2023). "In addition, we observed that CD38 deficiency markedly decreased diabetes or high glucose and palmitic acid (HG + PA)-induced pyroptosis and apoptosis in CD38 knockout hearts or cardiomyocytes, respectively." (PMID 37958991, 2023). "Moreover, we observed that the random blood glucose was reduced in the CD38-deficiency group compared with control mice under diabetes at 4, 6, and 8 weeks after HFD plus STZ injection." (PMID 37958991, 2023). "In addition, the bodyweight of CD38 deficient mice with diabetes was decreased compared with the control group, and CD38 deficiency significantly decreased the diabetes-induced increase in fasting glucose compared with control mice." (PMID 37958991, 2023). "However, it remains unknown whether CD38 participates in diabetes-induced cardiomyopathy and the underlying mechanisms." (PMID 37958991, 2023). "Its expression rises in both aging and diabetes, and experimental studies have shown that CD38 upregulation under hyperglycemic conditions reduces the NAD+/NADH ratio, promotes mitochondrial dysfunction, and exacerbates renal tubular injury." (PMID 41470091, 2025). "After adjusting for age, BMI, and diabetes duration in the multivariable model, CD38, NAMPT, and SIRT1 remained strong independent predictors of albuminuria, confirming that their associations were not confounded by these clinical covariates." (PMID 41470091, 2025). "In the present study, we observed that CD38 was up-regulated in the heart tissue of mice under diabetes, and Sirt3, which is mainly located in mitochondria, was down-regulated." (PMID 37958991, 2023). "In fasting and diabetes, nuclear CD38 prompts the production of ADP-ribose, triggering changes essential for generating the sustained calcium ion signals vital for responding to glucagon." (PMID 37394593, 2023). "The results showed that CD38 expression was significantly increased in protein and mRNA levels at 8 weeks following the onset of diabetes." (PMID 37958991, 2023). "In CD38 autoantibodies found in diabetes patients, some autoantibodies show agonistic effects on insulin secretion and others show antagonistic effects." (PMID 35457121, 2022). "Apigenin ameliorates the diabetes-induced renal tubular injury by reducing mitochondrial oxidative stress via CD38-mediated Sirt3 activation." (PMID 32507768, 2020).
diabetes (continued). "What is the mechanism by which diabetes and high glucose lead to CD38 overexpression in kidneys and tubular cells?" (PMID 32507768, 2020). "First, it is necessary to further investigate the roles of NAD+ and NAD+-dependent enzymes, including PARPs, sirtuins, and CD38, in multiple major diseases such as Alzheimer's disease, cancer, and diabetes." (PMID 24386592, 2013). "When analyzing the expression of co-receptors CD8 and CD38 on NK cells, we observed that CD38 is expressed on nearly 90% of NK cells under normal conditions, and this proportion remained unchanged in both types of diabetes." (PMID 41425544, 2025). "Therefore, CD38 has become a therapeutic target for treating infection, autoimmune diseases, aging, cancer, diabetes, and neurodegenerative disorders." (PMID 39682719, 2024). "As the NAD+ level is reduced in humans with various pathological conditions, including diabetes, inflammation, aging, rheumatoid arthritis, and neurodegenerative disorders, the inhibition of CD38 has become a therapeutic strategy for treating these pathological conditions." (PMID 39682719, 2024). "Follow-up data regarding the cardiorenal outcomes or metabolic changes including diabetes on the patients treated with CD38 antibodies may be useful to clarify the role of CD38 on cardiorenal metabolic disease in humans." (PMID 36831262, 2023). "Administration of apigenin reduced the CD38 expression and mitochondrial oxidative stress in diabetic kidneys, resulting in improved diabetes-induced renal injuries, such as tubulointerstitial fibrosis, tubular damage, inflammation, and urinary albumin/L-FABP excretion." (PMID 32507768, 2020). "CD38 has been linked to HIV infection, cancer, type 2 diabetes mellitus, and asthma." (PMID 28848387, 2017). "CD38 is also reported as target of autoantibodies in diabetes mellitus and SLE." (PMID 26886066, 2016). "ADPRCA in each subject is partly determined by preexistingfactors independent of diabetes, including CD38 genetic polymorphisms andautoantibodies against CD38." (PMID 19300526, 2008). "Finally, autoantibodies to CD38 have been detected in diabetes and thyroiditis and it would be interesting to identify the epitopic culprits." (PMID 15383153, 2004). "Furthermore, CD38 regulates insulin secretion and the progression of diabetes." (PMID 38921477, 2024). "In addition to NAD+ depletion, the increased expression of CD38 in diabetes involves the release of intracellular cADPR-mediated Ca2+ and mitochondrial damage, resulting in Nlr family pyrin domain-containing 3 (Nlrp3) inflammasome activation, VSMC proliferation and collagen I synthesis." (PMID 36831262, 2023). "We previously showed that mitochondrial oxidative stress in the kidneys of Zucker diabetic fatty rats is associated with a decreased intracellular NAD+/NADH ratio and NAD+-dependent deacetylase Sirt3 activity, and increased expression of the NAD+-degrading enzyme CD38." (PMID 32507768, 2020). "This study seeks to systematically examine blood concentrations and gene expression of CD38, NAMPT, and SIRT1 across several stages of albuminuria in individuals with type 2 diabetes mellitus." (PMID 41470091, 2025). "However, the role of CD38 in diabetes-induced cardiomyopathy is still unknown." (PMID 37958991, 2023). "Therefore, we investigated the frequency of these cells in diabetes, examining all CD56brightCD16- NK subtype 1 cells on a CD8/CD38 dot plot." (PMID 41425544, 2025). "It was shown that CD38 knockdown or treatment with CD38 inhibitors increases the NAD+ levels and ameliorates mitochondrial dysfunction and glucose intolerance in mice, leading to therapeutic interventions against Alzheimer’s disease, diabetes, and tumors." (PMID 38921477, 2024). "The screening of sera for autoantibodies against CD38 was performed in 377 Japanese type 2 diabetes patients and 75 non-diabetic controls who had no family history of diabetes and showed normal fasting plasma glucose levels." (PMID 35457121, 2022).